RNU6-894P (RNA, U6 small nuclear 894, pseudogene)
Gene: Small nuclear RNA gene on chromosome X (31,348,192 to 31,348,296, forward strand). Ensembl gene ENSG00000252903.
Homologues: Orthologues: macaque U6 (91% identical), chimpanzee U6 (90% identical), dog U6 (65% identical), rabbit U6 (63% identical), mouse Gm25792 (60% identical), guinea pig U6 (56% identical), rat LOC120103222 (55% identical). Paralogues in human: RNU6-1257P (76% identical), RNU6-116P (74% identical), RNU6-1050P (73% identical), RNU6-1060P (73% identical), RNU6-338P (73% identical), RNU6-959P (73% identical), RNU6-1181P (72% identical), RNU6-317P (72% identical), RNU6-949P (72% identical), RNU6-1024P (71% identical), RNU6-1201P (71% identical), RNU6-1251P (71% identical), and 1285 more.